TLR4 (toll like receptor 4)
Diseases named in the same sentence as TLR4 in open-access papers (continued):
Sharing a sentence is not in itself a finding about the gene and the disease.
rhinitis (2 papers, 2012 to 2022). An inflammation of the mucous membrane lining the nose, usually associated with nasal discharge. "Indeed, some extent of B. pertussis transmission and rhinitis could recently also be observed in infection experiments performed (with our involvement) in TLR4-deficient C3H/HeJ mice by the collaborating team of Dr. E.T. Harvill at University of Georgia." (PMID 35395059, 2022). "In conclusion, our data indicate that the pattern of expression of TLR4 and TLR is different in healthy subjects and in different forms of rhinitis, possibly in relation to the different pathophysiological mechanisms involved." (PMID 22577387, 2012). "The aim of the present study was to investigate the expression of TLR4 and TLR9 in the healthy and inflammatory nasal mucosa of different rhinitis phenotypes, by means of confocal analysis on paraffin sections of the inferior turbinates." (PMID 22577387, 2012). "This study shows that TLR4 and TLR9 are differently expressed in the nasal mucosa of healthy subjects and of the major rhinitis phenotypes." (PMID 22577387, 2012). "This study indicates that TLR4 and TLR9 show a different pattern of expression in different phenotypes of rhinitis, possibly related to the type and severity of the disease." (PMID 22577387, 2012).
Rickettsiosis (2 papers, 2018 to 2025). A group of infectious diseases that is caused by Rickettsia. "In a mouse model of rickettsiosis, TLR4/MD2 activation is critical for bacterial clearance; however, little is known about the contribution of LPS to the inflammatory nature of Rickettsia infection." (PMID 30012728, 2018). "According to the literature, both TLR2 and TLR4 are known as good Toll-like receptors for interaction in rickettsiosis, however TLR2 could be present a more exacerbated response and cause pathological effects." (PMID 40136144, 2025). "Additionally, lipid A is the endotoxic component of LPS, and activation of TLR4 is critical for bacterial clearance in mouse models of Rickettsia infection, as well as other intracellular parasites (49, –, 51)." (PMID 30012728, 2018).
Rotavirus infection (2 papers, 2014 to 2023). Infection with any of the rotaviruses. "It has been shown that the levels of TLR2 and TLR4 on various cells are increased during the initiation and modulation of the immune response to rotavirus infection, and that HMGB1 acts as a pro-inflammatory cytokine that causes persistent inflammatory responses via activation of TLR2 and TLR4." (PMID 24651485, 2014). "The protein-protein interaction (PPI) network analysis suggests that the TLR4/MyD88/NF-κB signalling pathway may be activated and SBP treatment restores the upregulation of inflammatory factors and downregulation of IFN-β due to rotavirus infection." (PMID 37006293, 2023).
salpingitis (2 papers, 2023 to 2026). Acute or chronic inflammation of the fallopian tube. "The results show that the protein expression levels of p65 and TLR4 were significantly downregulated in hucMSC-EV, suggesting that p65 and TLR4 may play an important role in the hucMSC-EV-mediated treatment of salpingitis." (PMID 36875046, 2023).
scrapie (2 papers, 2018 to 2022). A fatal disease of the nervous system in sheep and goats, characterized by pruritus, debility, and locomotor incoordination. "In agreement with the qPCR results, the TLR4 protein levels were significantly increased (p < 0.05) in all four brain regions of the scrapie-infected sheep." (PMID 35408945, 2022). "Our study clearly shows that TLRs, and especially TLR4 in sheep and TLR1 and TLR2 in mice, are involved in the pathogenesis of scrapie." (PMID 35408945, 2022).
selenium deficiency (2 papers, 2022 to 2023). A nutritional deficiency disease resulting from inadequate selenium levels in the body, which can lead to impaired function of selenoproteins essential for antioxidant defense and thyroid hormone metabolism. "Selenium deficiency induced oxidative stress and inflammation in pig adrenal tissue via the miR-30d-R_1/TLR4 pathway." (PMID 35799836, 2022). "The observed correlation between selenium deficiency and reduced levels of miR-30d-R_1, a microRNA (miRNA) known for its inhibitory effect on TLR4 expression, implies a potential link between the dysregulation of the TLR4/NF-kB pathway and the onset of inflammatory processes." (PMID 38098868, 2023).
sensitization (2 papers, 2011 to 2018). "Indeed, TLR2−/− mice developed increased eosinophils and goblet cells in the lung, while TLR4−/− mice did not, suggesting that CP-induced allergic sensitization requires TLR4 but not TLR2." (PMID 21695198, 2011).
septic peritonitis (2 papers, 2015 to 2023). Septic peritonitis is an inflammatory condition of the peritoneum that occurs secondary to microbial contamination. "We demonstrate a clear protective effect of the treatment with mAbs against TLR2 or TLR4 in a model of severe polymicrobial septic peritonitis induced by CLP." (PMID 26147469, 2015). "In addition, mast cells were found to be locally and systematically activated in a CLP-induced mouse model of septic peritonitis and TLR4 was shown to mediate LPS-induced mast cell activation." (PMID 37701780, 2023).
skin aging (2 papers, 2023). The gradual irreversible changes in structure of skin that occur as a result of the passage of time.. "Secondly, a different model than LPS and TLR4-mediated signaling, such as H2O2-induced inflammation, could be more relevant in the context of skin aging." (PMID 37373433, 2023).
skin sensitization (2 papers, 2020 to 2021). An immunological response to previous exposure to a substance which results in an inflammatory skin reaction. "NiSO4 and cobalt are known to induce TLR4-dependent IL-8 production, which is defined as a key event for skin sensitization." (PMID 33777040, 2021).
ST Elevation Myocardial Infarction (2 papers, 2021). A myocardial infarction that produces elevation in the ST segments of the ECG. "Further activation of this inflammatory pathway is likely to occur with clinical events, as an elevation in TLR4 has been seen in both ST-elevation myocardial infarction (STEMI) and Non-ST-elevation myocardial infarction (NSTEMI) compared to CAD." (PMID 34502027, 2021).
Streptococcus pneumonia (2 papers, 2014 to 2021). "It has also been shown that TLR4 plays a role in the pulmonary host defence against bacteria, as exemplified by Haemophilius influenza and Streptococcus pneumonia." (PMID 25089623, 2014). "However, some research reported that IL-1β secretion was independent of activation of TLR4 in Streptococcus pneumonia and Streptococcus suis-infected cells in vitro." (PMID 34017331, 2021).
substance abuse (2 papers, 2018 to 2021). The use of a drug for a reason other than which it was intended or in a manner or in quantities other than directed. "For example, TLR-4 can recognize bacterial LPS and induce immune responses, and the overactivation of TLR-4 in the periphery may play an important part in stress-related mental illnesses and substance abuse." (PMID 30271330, 2018).
tauopathy (2 papers, 2021 to 2024). Neurodegenerative disorders involving deposition of abnormal tau protein isoforms (tau proteins) in neurons and glial cells in the brain. "We utilized a transgenic mouse model of tauopathy subjected to chronic TLR4 stimulation via weekly intraperitoneal injections of LPS over nine consecutive weeks." (PMID 39503044, 2024).
tendinopathy (2 papers, 2017 to 2023). "Tenocytes can be transformed from a quiescent state to an activated state by the inflammatory reaction of tendinopathy, being hypertrophic ones and highly expressing molecular markers such as toll-like receptor 4 (TLR4), interferon regulatory factor 1 (IRF1), IRF5, PDPN, CD106, and CD248." (PMID 37545895, 2023). "We propose HMGB1 as a mediator driving the inflammatory/matrix crosstalk and manipulation of the HMGB1/TLR4 axis may offer novel therapeutic approaches targeting inflammatory mechanisms in the management of human tendon disorders." (PMID 28879051, 2017). "Herein we demonstrate that HMGB1 is present in early tendinopathy biopsies and thereafter in mechanistic studies demonstrate that HMGB1 likely contributes to regulation of inflammatory and matrix pathways in tendon cells via TLR4 signalling." (PMID 28879051, 2017).
Thiamine deficiency (2 papers, 2022 to 2025). Thiamine deficiency is a condition that occurs due to not enough thiamine (vitamin B1). "Additionally, thiamine deficiency appears to be implicated in the upregulation of TLR4 and NLRP3 pathways, further perpetuating cellular energy deficits and oxidative stress." (PMID 40700076, 2025).
Tinnitus (2 papers, 2025). Tinnitus is an auditory perception that can be described as the experience of sound, in the ear or in the head, in the absence of external acoustic stimulation. "This Mendelian randomization study reveals that elevated CCL19 increases tinnitus risk via pantothenate‐mediated inflammation, implicating the CCL19‐pantothenate‐TLR4/NF‐κB axis as a causal pathway." (PMID 40898658, 2025). "For example, TLR4 is targeted by cyclobenzaprine, which is currently used to treat tinnitus, NOS2 can be targeted by dexamethasone and gingko biloba, which are also already used to treat tinnitus." (PMID 40217670, 2025).
trypanosomiasis (2 papers, 2018 to 2022). Infection with protozoa of the genus trypanosoma. "In this study, pentamidine, an approved drug used in the treatment of trypanosomiasis, was identified as a TLR4 antagonist." (PMID 35281916, 2022).
typhoid fever (2 papers, 2009 to 2013). A bacterial infectious disorder contracted by consumption of food or drink contaminated with Salmonella typhi. "Here we determine the genetic variation within the human TLR4 gene encoding the principal receptor for bacterial endotoxin recognition in typhoid fever patients." (PMID 19277200, 2009). "Here we report the detection and genotyping of mutations within the TLR4 gene in typhoid fever patients and controls in the Vietnamese population." (PMID 19277200, 2009). "Mutation detection and genotyping of TLR4 was performed on DNA from 414 Vietnamese typhoid fever patients and 372 population controls." (PMID 19277200, 2009). "Here we determined the extent of genetic variation within TLR4 in a Vietnamese population and suggest that TLR4 may be involved in defense against typhoid fever in this population." (PMID 19277200, 2009).
uterine disease (2 papers, 2009 to 2020). "It has been demonstrated that the LPS-induced dysregulation of prostaglandin secretion is linked with the Toll-like receptor 4 (TLR4) signaling pathway, which explains the prolonged luteal phase in the bovine uterine disorders." (PMID 32545766, 2020).
ventilator-associated pneumonia (2 papers, 2018 to 2022). Serious INFLAMMATION of the LUNG in patients who required the use of PULMONARY VENTILATOR. "In another study, TLR4 mRNA was shown to be regulated by miR-1236, which leads to risk of development of VAP (ventilator-associated pneumonia) in COPD." (PMID 35008971, 2022). "Combination of TLR4 and TIRAP SNPs has been described to be associated with low circulating levels of TNF-α and IL-6 in adult patients with ventilator-associated pneumonia following 1 ng/ml LPS-stimulation." (PMID 30131804, 2018).
vesicoureteral reflux (2 papers, 2019 to 2022). Abnormal flow of urine from the urinary bladder back into the ureters. "It was also found that the TLR4 299AG genotype and the TLR4 299G alleles were also observed more frequently in children with recurrent UTI without vesicoureteral reflux (VUR) than in children with VUR." (PMID 31183391, 2019).
vitiligo (2 papers, 2021). Generalized well circumscribed patches of leukoderma that are generally distributed over symmetric body locations and is due to autoimmune destruction of melanocytes. "The significant relationship between TLR4 gene polymorphisms and vitiligo patients charcteristics clarify the role of innate immunity in pathogensis of vitiligo and its effect on the used therapies." (PMID 34468896, 2021). "In our study, TLR4 rs11536858, rs1927914, and rs1927911 gene polymorphisms were examined in 100 Egyptian patients diagnosed with vitiligo versus 100 controls." (PMID 34468896, 2021). "The aim of this study is to identify if there is an association between TLR4 polymorphisms; namely rs1927914, rs11536858, and rs1927911 genotypes; and the risk of vitiligo in Egyptian patients, their clinical data, and their response to therapy." (PMID 34468896, 2021). "The purpose of this study was to investigate the possible association between TLR4 gene polymorphisms: rs11536858, rs1927911, rs1927914 in Egyptian vitiligo patients and their clinical data, their response to therapy." (PMID 34468896, 2021). "Using PCR-RFLP for TLR4 gene polymorphisms (rs11536858, rs1927911, and rs1927914), both alleles and genotypes were determined after extraction of DNA in a case-control study of 100 vitiligo Egyptian patients and 100 matched age and sex controls." (PMID 34468896, 2021).
wheat allergies (2 papers, 2018 to 2025). "They investigated the relationship between polymorphism at the TLR4 locus and the risk of developing respiratory wheat allergy." (PMID 40077585, 2025). "Lower risk of respiratory wheat allergy was associated with TLR4 polymorphism as follows: homozygotes for the −2027 G and −1608 C alleles (n = 381, adults, South Korean bakers study)." (PMID 40077585, 2025). "They found that the homozygous variant of two TLR4 alleles was associated with significantly reduced risk of developing respiratory wheat allergy." (PMID 40077585, 2025).
Zinc deficiency (2 papers, 2022). A deficiency of the essential metal Zinc; an essential cofactor for many enzymes. "Similar to our results, studies in both murine and human primary monocytes had shown zinc deficiency to impair TLR4-mediated signaling that resulted in reduced production of cytokines such as TNF-α, IL-6, IL-10, and Il-1β." (PMID 36558553, 2022). "In vitro studies in human monocytes had shown zinc deficiency to impair TLR-4-mediated signaling that resulted in decreased cytokine responses." (PMID 36558553, 2022). "In this study, marginal zinc deficiency increased (p < 0.05) the relative expression of NF-κB, though TLR-4 was not significantly different in mice with ETEC infection." (PMID 36136723, 2022).
Acinetobacter infections (1 paper, 2019). "TLR4 signaling is essential for initiating inflammatory responses in vitro and in vivo to clear Acinetobacter infections." (PMID 30745327, 2019).
Acute hepatic failure (1 paper, 2022). "The most prominent hepatic TLRs are TLR2 and TLR4 have been shown to be important for the production of the inflammatory response observed in different models of experimental hepatic injury such as hepatic ischemia, inflammation, and acute hepatic failure." (PMID 35517830, 2022).
adenosquamous carcinoma (1 paper, 2021). A carcinoma composed of malignant glandular cells and malignant squamous cells. "In addition, ACG treatment remarkably down-regulated the expression of TLR4, p-P65, NLRP3, Caspase-1 and adenosquamous carcinoma (ASC) in lung tissue." (PMID 33645621, 2021).
Adrenal insufficiency (1 paper, 2018). Insufficient production of steroid hormones (primarily cortisol) by the adrenal glands. "SND increased overall survival rate within 4 days and attenuated adrenal insufficiency in septic rats by downregulating TLR4 mRNA and protein expression in adrenal tissue, inhibiting adrenal production of TNF-α and IL-10, and improving adrenal responsiveness." (PMID 30018657, 2018).
adrenocortical tumors (1 paper, 2013). "Three major pathogenetic pathways including lipopolysaccharide/Toll like receptor 4 pathway are novel pathological mechanisms of adrenocortical tumors and associated genes may be markers and therapeutic targets of malignancy." (PMID 24376526, 2013).
aging (1 paper, 2018). A developmental process that is a deterioration and loss of function over time. "Differential expression of specific proteins involved in the TLR4/ERK pathway may explain the severity of skin aging by replicative senescence." (PMID 30118525, 2018).
Airway obstruction (1 paper, 2013). Obstruction of conducting airways of the lung. "In this study, wild-type(WT) and TLR4-deficient mice (TLR4−/−) were infected with hMPV and examined for clinical disease parameters, such as body weight loss and airway obstruction, viral clearance, lung inflammation, dendritic cell maturation, T-cell proliferation and antibody production." (PMID 24205331, 2013). "Our results show that mice lacking TLR4, infected with hMPV, showed less clinical disease, demonstrated by significantly reduced body weight loss and less airway obstruction and AHR, compared to WT mice." (PMID 24205331, 2013). "Our results demonstrate that absence of TLR4 in hMPV-infected mice significantly reduced the inflammatory response as well as disease severity, shown by reduced body weight loss and airway obstruction and hyperresponsiveness (AHR), compared to WT mice." (PMID 24205331, 2013).
allergic bronchopulmonary aspergillosis (1 paper, 2015). Allergic bronchopulmonary aspergillosis (ABPA) is a rare immunologic pulmonary disorder caused by hypersensitivity to Aspergillus fumigatus, clinically manifesting with poorly controlled asthma and recurrent pulmonary infiltrates. "In addition, TLR9(T1237C) also had increased prevalence in allergic bronchopulmonary aspergillosis, while TLR4(Asp299Gly) had significant association with chronic cavitary pulmonary aspergillosis." (PMID 26361369, 2015).
amnesia (1 paper, 2023). Pathologic partial or complete loss of the ability to recall past experiences ( AMNESIA, RETROGRADE) or to form new memories ( AMNESIA, ANTEROGRADE). "The cascade of reactions can lead to apoptosis, necrosis, Ca2+ overload, protein aggregation, and mitochondrial dysfunction, affecting various signaling pathways (PI3K/AKT, TLR-4/NF-kB, Nrf/HO-1, ERK/p38/JNK] and eventually causing amnesia and brain damage." (PMID 38201932, 2023).
anaphylaxis (1 paper, 2018). An acute hypersensitivity reaction that occurs from exposure to an allergen. "There have been differing reports on the role of TLR4 in susceptibility to food-induced anaphylaxis, but we have found that C3H mice are susceptible to food-induced anaphylaxis independent of TLR4 mutations." (PMID 29370173, 2018).
anaplastic astrocytoma (1 paper, 2022). "Other studies revealed that the expression of TLR4 was significantly higher in GBM than in grade III anaplastic astrocytoma, and was correlated with poor patient prognosis." (PMID 36248827, 2022).
aortic stenosis (1 paper, 2014). Aortic valve stenosis is a aortic valve disease caused by the incomplete opening of the aortic valve. "In light of our findings, therapeutic interference with S1P receptor and TLR4 signaling could be a potentially useful strategy to slow down aortic stenosis progression by avoiding inappropriate inflammatory responses." (PMID 25275309, 2014). "Moreover, the pair S1P receptors-TLR4 may be potential targets for aortic stenosis treatment since S1P cooperates with LPS to induce synergistic inflammatory, angiogenic, and osteogenic responses." (PMID 25275309, 2014).
appendicitis (1 paper, 2017). Acute inflammation of the vermiform appendix. "TLR4/MYD88/NF-κB signaling pathway was activated in acute phase of appendicitis." (PMID 29029533, 2017). "This study was conducted to evaluate the immune impact of mimic endoscopic retrograde appendicitis therapy and appendectomy on rabbits of acute suppurative appendicitis and to determine whether TLR4/MYD88/NF-κB signaling pathway was activated in this process." (PMID 29029533, 2017).
artery disease (1 paper, 2023). "At the sametime, a clinical study showed that the combination therapy of statins(atorvastatin) and telmisartan (angiotensin II receptor blocker, ARB) reducedboth miR-146a/b-5p and Toll-like receptor 4 (TLR4) signaling in patients withcoronary artery disease." (PMID 39076378, 2023).